TDH (L-threonine dehydrogenase (pseudogene))
Synonyms: SDR14E1P; TDHP; FLJ25033
Gene: Transcribed unitary pseudogene on chromosome 8 (11,356,120 to 11,365,722, forward strand). Ensembl gene ENSG00000154316.
Subcellular location: Mitochondrion
Diseases named in the same sentence as TDH in open-access papers:
TDH is named in the same sentence as 9 diseases in open-access papers, as found by Europe PMC text mining. Sharing a sentence is not in itself a finding about the gene and the disease. The quoted sentences say what the papers report.
glioma (4 papers, 2015 to 2022). A benign or malignant brain and spinal cord tumor that arises from glial cells (astrocytes, oligodendrocytes, ependymal cells). "Six pseudogenes (SP3P, ANXA2P3, PTTG3P, LPAL2, CLCA3P, and TDH) were reported to be associated with overall survival in glioma." (PMID 36333286, 2022). "A prior report that constructed another signature with six pseudogenes (SP3P, ANXA2P3, PTTG3P, LPAL2, CLCA3P, and TDH) for prediction of glioma patient survival." (PMID 31681595, 2019). "TDH mRNA was present in most cell types examined, but was below the level of detection in endothelial cells, glioma cell lines and some leukaemia cell lines according to the study of Alasdair J Edgar." (PMID 25880120, 2015). "As the expression of TDH mRNA was low in glioma cell line, we conjectured that TDH might serve as an endo-generate siRNA, or work as a molecular sponge combining microRNAs." (PMID 25880120, 2015). "Notably, 5/14 OPR-DEGs, including TDH, SSTR5, HMGN5, LGR6, and SEL1L3, also have different expressions between high-risk patients and low-risk patients in the TCGA PTEN-wt subgroup (p < 0.001), suggesting that they are associated with the prognosis of PTEN-wt glioma." (PMID 34336645, 2021).
diabetes (1 paper, 2020). "The NEGR1 gene, along with TDH and FAM167A-AS1, also associated with impaired fasting glucose and diabetes, respectively, at a slightly lower, yet still significant p-values." (PMID 31888951, 2020).
gastroenteritis (1 paper, 2023). An inflammatory disorder that affects the upper and lower gastrointestinal tract. "Eating any raw V. parahaemolyticus-contaminated seafood can lead to gastroenteritis because the pathogen contains various virulence factors, including adhesin, heat-resistant direct hemolysin (TDH), TDH-associated hemolysin, and the type III secretory system." (PMID 37127579, 2023).
infection (1 paper, 2018). The state of being infected such as from the introduction of a foreign agent such as serum, vaccine, antigenic substance or organism. "To avoid the cytotoxic effects of TDH and T3SS1, we therefore used the POR-2 strain as a parental strain for the in vitro infection assay to focus on the T3SS2-dependent effect." (PMID 30042203, 2018).
myopathy (1 paper, 2024). A disease of the muscle in which the muscle fibers do not function properly. "The TDH and RGCC genes were upregulated in the PMM of WS-affected chickens and, although not involved in the BPs identified in this study, were related to WS for the first time, establishing them as key functional candidates for myopathy development." (PMID 39199913, 2024).
TDH also shares sentences with these, for which no sentence is quoted: Chagas disease (1 paper); chronic spontaneous urticaria (1); leukaemia (1); pancreatic carcinoma (1).